KRAS (KRas proto-oncogene, GTPase)
Diseases named in the same sentence as KRAS in open-access papers (continued):
Sharing a sentence is not in itself a finding about the gene and the disease.
tumor (continued). "Other pertinent up-regulated miRNAs of interest on this elagolix-treated array include miR-1205, acting like a tumor suppressor by inhibiting KRAS." (PMID 38999962, 2024). "Upon examining how KRAS mutations and MYC dysregulation tailor the TIME and impact different immune populations in several tumor types, it is apparent that they share several mechanisms." (PMID 39164274, 2024). "Previous literature indicates that KRAS mutations and activation are critical genetic drivers of PDAC occurrence and progression and are crucial for maintaining PDAC tumor growth." (PMID 39519347, 2024). "In NSCLC cell line (A549) with KRAS G12S mutation, the combination of mitogen-activated protein kinase (MEK) inhibitor trimetinib and IK-930 exerted a synergistic anti-tumor effect." (PMID 38499647, 2024). "IBI351 exerts its anti-tumor effects by directly inhibiting the mitogen-activated protein kinase signaling pathway through downregulation of KRAS." (PMID 39433508, 2024). "Targeted degradation of KRAS G12V reprograms the tumor microenvironment and triggers antitumor immunity." (PMID 39718828, 2024). "Given that PDAC is an immunologically “cold” tumor, remodeling the tumor microenvironment with KRAS inhibitors has the potential to lead to combinations with immune checkpoint inhibitors." (PMID 38800401, 2024). "It encapsulates recent strides made in understanding KRAS biology’s mechanistic nuances, shedding light on pivotal themes such as drug resistance, anti-tumor immune responses, epigenetic regulation, and the exploitation of synthetic lethality by mutant KRAS." (PMID 38275900, 2024). "A recent study concluded that autophagy is dispensable in KRAS‐mutant tumor cells, despite the fact that autophagy is necessary for tumorigenic growth." (PMID 39436197, 2024). "Despite this generally accepted view, KRAS and EGFR mutations can rarely occur within the same tumor." (PMID 38953007, 2024). "Micro-CT scanning at the end of the 2 weeks of treatment revealed that KRAS inhibition with RMC-4998 resulted in 100% regressions in most of the tumours." (PMID 39322643, 2024). "Together these data indicate that STAT3 is a genetic modifier that can regulate KRAS dependency and tumor development through counterposing EMT." (PMID 38573819, 2024). "Among them, GINS3 was characterized by high tumor purity, immune-desert, activation of EGFR and ephrin receptors, chromosomal instability, fewer KRAS mutations, SMOC1 methylation, immunotherapeutic resistance, and high sensitivity to cetuximab and bevacizumab." (PMID 38429655, 2024). "Phase 1 and 2 clinical trials demonstrated significant tumor reduction in patients with G12C KRAS-positive NSCLC, with an objective response rate (ORR) of about 37% and a median PFS of 6.8 months." (PMID 39199653, 2024). "PRRX1 overexpressed in MPNSTs directly interacts with topoisomerase 2 A (TOP2A) to cooperatively promote epithelial-mesenchymal transition and increase expression of tumour malignancy-related gene sets including mTORC1, KRAS and SRC signalling pathways." (PMID 38448751, 2024).
tumor (continued). "The patient’s tumor was found to contain somatic mutations in APC (p.Q1549*), APC (p.R904fs), SMAD4 (p.R135*), SMAD4 (p.A190fs), ATR (p.F134fs) and KRAS (p.G12D)." (PMID 38243056, 2024). "As part of the trial, the mutation status of KRAS (exon 2, 3, and 4), NRAS (exon 2 and 3), and BRAF (codon 600) was previously assessed in tumor tissue." (PMID 39433569, 2024). "Further, Afatinib, an approved pan-ERBB inhibitor, was shown to reduce KRAS-driven tumor growth in multiple mouse models, whereas erlotinib or gefitinib did not." (PMID 38659041, 2024). "Although the addition of CQ to MEK1/2 or ERK1/2 inhibition increased the therapeutic response in multiple KRAS-driven tumor models, the observed potency of these combinations is still modest." (PMID 38842946, 2024). "Several studies have assessed the utility of mutant KRAS subtyping in circulating tumor DNA (ctDNA)." (PMID 38610868, 2024). "Future research should investigate the potential applications of IRF7/IFNβ in KRAS mutant CRC, as well as the regulation of tumor-associated microbial ecology through the miR3655/SURF6 axis, providing insights into personalized treatment strategies." (PMID 39523457, 2024). "In light of these findings, combining SHP2 and KRAS G12C inhibitors offers a promising approach for treating KRAS-mutant tumors by reshaping the tumor’s immune landscape to counter resistance mechanisms." (PMID 38668053, 2024). "KRAS and KRAS-LKB1 mutations were induced, and the tumor formation and progression were monitored over time." (PMID 39763604, 2024). "Mechanistically, circ_0039787 promotes CC tumor progression by competitively absorbing miR-877-5p to alleviate the inhibitory effect of miR-877-5p on Kirsten Rat Sarcoma viral oncogene homolog (KRAS) expression." (PMID 38309290, 2024). "For instance, where Myc is specifically expressed in oncogenic KRas-driven lung epithelial tumour cells, Myc expression leads to a reversible influx of VEGF-expressing macrophages, an exclusion of T cells, and rapid onset of angiogenesis." (PMID 38577503, 2024). "For example, the addition of MEK to KRAS G12C inhibition, as seen with the combination of trametinib and sotorasib, has exhibited anti-tumor efficacy and an acceptable safety profile in advanced KRAS G12C-mutated solid tumors." (PMID 39337530, 2024). "Our data identifies the transcriptional effector YAP1 as impacting tumor-intrinsic gene expression in STK11-deficient, KRAS-driven human LUAD cell lines." (PMID 37968341, 2024). "According to recent research, patients with higher KRAS VAF exhibited greater tumor cellularity and worse survival outcomes." (PMID 38525415, 2024). "A clinical trial has been conducted using long peptide vaccines targeting KRAS p.G12D/R mutations in 20 PDAC and 5 CRC patients, where 84% exhibited specific T cell responses to KRAS p.G12D/R and observed tumor biomarker responses." (PMID 39066355, 2024). "Conversely, preventing nuclear protein export contributes to the antitumor activity of KRAS inhibition, which can be further augmented by reactivating the tumor suppressor activity of DLC1 or potentially combining RAS inhibitors with other cancer treatments." (PMID 39528835, 2024). "RMC-7977, a compound that exhibits potent inhibition of the active states of mutant and wild-type KRAS, NRAS and HRAS variants has a strong anti-tumour effect on RAS-addicted tumours and is well tolerated in preclinical models." (PMID 38589574, 2024). "Here, we demonstrate a critical role for wild-type KRAS in tumour initiation and progression of mutant KRAS-driven tumours." (PMID 38168062, 2024).
tumor (continued). "In selected cases enrichment of cancer gene mutations, such as copy number gain of MYC and KRAS, and pathogenic variants of IDH1 and STK11, was observed in residual tumor cells following study therapy." (PMID 38689060, 2024). "On the other hand, TEAD can play an important role in tumor progression, metastasis, tumor metabolism, immunity and drug resistance through transcription and regulation of KRAS, BRAF, LKB1, NF2 and MYC." (PMID 38553612, 2024). "Glutamate is highly expressed in PDAC tissues and promotes tumor migration by activating the KRAS-MAPK signaling pathway." (PMID 38081962, 2024). "The hormone-sensitive lipase (HSL) was identified as a key player, with its suppression by oncogenic KRAS contributing to tumor cell invasion." (PMID 38666907, 2024). "This includes the development of mutant-selective inhibitors, particularly those targeting the KRAS G12C mutation, as well as the exploration of immunotherapies aimed at RAS-mutant neoplasms." (PMID 39518114, 2024). "After confirming that dTAGV-1 successfully degraded FKBP12F36V-KRASG12V and inhibited oncogenic KRAS signaling, we proceeded to assess its effect on tumor growth in vivo." (PMID 39718828, 2024). "Nonetheless, a clear understanding of the mechanistic basis of wild-type KRAS function in the processes of tumour initiation and progression of KRAS mutant tumours is yet to be defined." (PMID 38168062, 2024). "The study found a significant correlation between T cell responses and tumor biomarker reduction, indicating that ELI-002 2P is safe and effective in inducing T cell responses in KRAS-mutated tumors." (PMID 39054529, 2024). "Other tumour growth-related genes, such as Myb, KRAS, Akt-3, and CDK4 were also downregulated by the three BRD4 inhibitors in PDAC cells." (PMID 38279262, 2024). "There are cases of relapse in advanced CRC patients treated with EGFR-targeted monoclonal antibody therapy and this involves the outgrowth of previously undetected KRAS-mutant tumor cell populations." (PMID 39125664, 2024). "Our findings are expected to establish an oncogene‐driven combinatorial treatment strategy to potentiate the anti‐tumor activity of both CDK9i and KRAS signaling inhibitors, while concurrently mitigating immunosuppression and overcoming drug resistance." (PMID 39254172, 2024). "As a signaling protein, KRAS is involved in many intracellular signaling pathways that regulate processes such as tumor cell growth and angiogenesis." (PMID 38309290, 2024). "Among them, AZD4785 stands out as a highly efficient and selective KRAS-targeting antisense oligonucleotide, capable of specifically silencing KRAS and significantly inhibiting MM tumor growth both in vitro and in vivo." (PMID 38961036, 2024). "CRISPR/Cas9 can be used to specifically target, and knock-out, mutated or overexpressed oncogenes, such as MYC, KRAS, and EGFR, which drive tumor growth and progression." (PMID 39696697, 2024). "The TME changes upon KRAS-targeted therapy rendering tumors vulnerable to an immunotherapy combination regimen that resulted in tumor clearance and immune memory." (PMID 38727236, 2024).
tumor (continued). "Oncogenic KRAS in tumor cells can inhibit the expression of IRF2, leading to high expression of CXCL3, which promotes the migration of myeloid-derived stem cells into the TME17." (PMID 38992029, 2024). "GSEA revealed that CBX3 knockdown modulated expression of genes related to tumor escape from immune attack, KRAS signaling, IL-6 receptor-ligand interaction, and STAT3 activity." (PMID 39545414, 2024). "The addition of panitumumab to these regimens led to a reduction in PFS for both wt and mutant KRAS tumor patients compared with those receiving FOLFOX or FOLFIRI with bevacizumab alone." (PMID 38254903, 2024). "In KRAS mutation group, high P4HA2 expression is the only independent prognostic factor for tumor recurrence, so it can be suggested to be a novel target for therapy." (PMID 38522060, 2024). "In the preclinical tumor cell line model, Nicolantonio and colleagues observed drug insensitivity in the co-mutation of PIK3CA and KRAS." (PMID 39056802, 2024). "Sotorasib is the first FDA-approved drug that irreversibly and selectively inactivates KRAS G12C, blocking the signaling pathway that promotes tumor growth." (PMID 39199653, 2024). "Mutation in different oncogenes such as KRAS, cMYC, EGFR, and HER can affect the immune cell activity in the tumor microenvironment (TME) through distinct mechanisms." (PMID 39201585, 2024). "Two factors (tumor size and KRAS VAF) that exhibited significant differences between tumors with and without rim enhancement were further evaluated with ROC curves." (PMID 38525415, 2024). "Here, we identify that F. nucleatum is enriched preferentially in KRAS p.G12D mutant CRC tumor tissues and contributes to colorectal tumorigenesis in Villin-Cre/KrasG12D+/- mice." (PMID 38402201, 2024). "In conclusion, we found that trametinib activates the proteasome to reduce Id1 levels in KRAS-mutant LUAD tumor cells." (PMID 38643157, 2024). "In KRAS/LKB1 models, the locomotion reduction appeared more pronounced than in KRAS mice, possibly reflecting the aggressive nature of these tumor subtypes." (PMID 39763604, 2024). "In PDAC with KRAS mutation, inhibition of the MAPK pathway promotes tumor-protective autophagy, and combination therapy with both ERK and autophagy inhibitors has a synergistic effect, whereas either alone has a weaker effect." (PMID 38684511, 2024). "For instance, RAS signaling via the AP-1 complex transcriptionally activates IL11 gene expression in cancer cells, while KRAS-mutant cells are poised to coerce cells of the tumor microenvironment into the production of cytokines." (PMID 39128004, 2024). "Radiogenomics is an emerging field that aims to identify the relevant genotypic features of tumours such as KRAS/NRAS/BRAF that guide targeted therapy." (PMID 39272969, 2024). "Antitumor activity was particularly notable in tumor models dependent on KRAS position 12 mutations (KRASG12X), albeit clearly extended to models with other KRAS hotspot mutations." (PMID 38593348, 2024). "The protumoral phenotype conferred by Id1 expression in KRAS-mutant LUAD has been related to the induction of tumor angiogenesis, tumor-associated immunosuppression and metastasis." (PMID 38643157, 2024). "Treatment with PLD1 inhibitors significantly decreases tumor growth in mice bearing PDXs with PIK3CA and KRAS mutations and in mice bearing PDXs with APC and KRAS mutations." (PMID 38945955, 2024).
tumor (continued). "We found contrasting associations of immune cell infiltration in KRAS-mutated and BRAF-mutated CRC tumours." (PMID 38040818, 2024). "They do this through the bidirectional communication between KRAS and the inflammatory factors released by tumor cells themselves." (PMID 39020414, 2024). "The incidence of KRAS mutations in CCA displays significant variability across study populations and tumor locations." (PMID 38730642, 2024). "MET amplification has also been identified as a mediator of resistance in NTRK fusion positive tumor and KRAS G12C mutant subtype of NSCLC." (PMID 38485737, 2024). "Herein, we more than doubled the size of our population and still observed the same performance, with SS detecting KRAS mutations in 51% of tumor samples (n = 45) and ARMS–HRMA detecting mutations in 77% of tumor samples (n = 68)." (PMID 39456638, 2024). "Oncogenic KRAS drives pancreatic carcinogenesis by acting on both epithelial cells and tumor microenvironment (TME)." (PMID 39342278, 2024). "Utilizing Leptotrichia-derived Cas13a proteins and optimized crRNAs demonstrated robust knockdown of KRAS-G12D mRNA, inhibiting downstream signaling pathways and impeding tumor growth in vivo." (PMID 38666907, 2024). "DCs were pulsed by tumor cell lysates or KRAS G12D1 − 23 peptide, and then used to activate T cells." (PMID 38554155, 2024). "The idea that mutant KRAS gene dosage or allelic configuration can alter tumour progression has been explored recently." (PMID 38168062, 2024). "STAT3 sustains the KRAS-dependent phenotype and tumor aggressiveness, with the potential for improved efficacy of anti-RAS drugs, whereas SMAD4 promotes KRAS independence at the expense of enhanced therapy resistance." (PMID 38573819, 2024). "Using preclinical experimental models, we have shown that trametinib and PD-1 blockade combined treatment significantly reduced KRAS-mutant LUAD tumor growth in a synergistic manner." (PMID 38643157, 2024). "Other genes such as APC, KRAS, VHL and IDH1 were highly enriched for mutations in only one or two tumor types." (PMID 38200255, 2024). "Oral treatment with these compounds shows anti-tumor effects in preclinical models and has shown an ability to maintain KRAS in the inactive GDP-bound state." (PMID 39125664, 2024). "Regarding the upregulation of KRAS signaling in NMP organoids, it is well-established that KRAS mutations are a hallmark of PDAC, promoting tumor growth and survival." (PMID 38619751, 2024). "It has been reported that varying amino acid substitutions in KRAS can result in different aberrations in multiple biological processes of tumor." (PMID 38619751, 2024). "To assess the role of STAT3 in KRAS-driven tumorigenesis, we measured proliferation rates, contact inhibition, and tumor formation in mice." (PMID 38573819, 2024). "KRAS activation has been reported to function as a master regulator, affecting the properties of multiple tumor microenvironment components and promoting cancer progression by mobilizing cells such as fibroblasts, macrophages, neutrophils, and lymphocytes." (PMID 38528852, 2024).